AQP4 (aquaporin 4)
Diseases named in the same sentence as AQP4 in open-access papers (continued):
Sharing a sentence is not in itself a finding about the gene and the disease.
tumor (continued). "Within the 37-gene-set, we highlight GPM6A (Glycoprotein M6A), ABAT (4-Aminobutyrate Aminotransferase), GFAP (Glial Fibrillary Acidic Protein), and AQP4 (Aquaporin-4), known to play roles in tumor invasion and progression within various cancers." (PMID 40575267, 2025). "Elevated expression and mislocalization of AQP4 around tumor boundaries are strongly correlated with the extent and severity of peritumoral edema." (PMID 41324079, 2025). "Peritumoral astrocytic mislocalization of AQP4, together with tumor mass effect, compromises glymphatic function by distorting perivascular spaces and compressing cerebrospinal fluid (CSF)-Interstitial fluid (ISF) exchange zones." (PMID 41324079, 2025). "The first hit involves a tumor ectopically expressing the AQP4 protein, which breaks immune tolerance and leads to the production of pathogenic AQP4-IgG." (PMID 40963604, 2025). "High AQP4 expression was negatively correlated with several investigational agents, including STK527948 (NSC663954), suggesting potential sensitivity in AQP4-overexpressing LUAD tumours." (PMID 41007424, 2025). "have discovered the potential relationship between AQP4 and immune variables that influence tumour progression." (PMID 39247976, 2024). "Chelerythrine’s suppression of PKC decreased AQP4 phosphorylation while increasing water porousness and tumour cell migration." (PMID 38336645, 2024). "They observed that macrophages related to tumours in the patients with elevated AQP4 group tended to become polarized towards M2 macrophages." (PMID 39247976, 2024). "Emerging evidence suggests a positive relationship between AQP1 and AQP4 expression and histological tumor grade and brain edema volume." (PMID 38476871, 2024). "Previous studies have shown that enhanced phosphorylation of AQP4 can reduce water permeability and decrease the invasiveness of tumor cells." (PMID 36599974, 2023). "Seizures can arise due to alterations in potassium buffering, resulting in elevated levels of the potassium ion channel Kir4.1 or the water channel aquaporin-4 (AQP-4) on tumour cells." (PMID 38067243, 2023). "Tumor cells of high AQP4 and low AQP4 groups were separately pooled, dimension reduced, and normalized via Monocle 3 R package." (PMID 36599974, 2023). "This substantial shape change is mediated by water flow through aquaporins AQP1 and AQP4 (discussed in Section 5, Tumor Microenvironment) and is guided by ion flux of primarily K+ and Cl− channels." (PMID 36768856, 2023). "Although NAPi2b and AQP4 have been shown as the promoting factors for tumor progression, invasion, and metastasis, these two transporters mediate the homeostasis of cellular phosphate uptake and water flow." (PMID 37108455, 2023). "In other organs, comparably, AQP4 expressions are at very low levels in both tumor and paired normal tissues, consistent with previous studies." (PMID 36599974, 2023). "Although a number of patients with AQP4-IgG-positive NMOSD and co-existing cancer (with AQP4 expression within the tumor tissue in some) have been reported, the disorder is not tumor-associated in the vast majority of cases." (PMID 37022481, 2023). "Expression levels of AQP4 were correlated with the edema index (EI), a parameter previously used to evaluate the extent of edema correlated to tumor volume." (PMID 35187599, 2022). "Increased AQP4 expression has been seen in high grade tumours and a variety of roles suggested including water permeability and glial cell migration, with AQP4 knockout glial cells having reduced migratory and invasion ability." (PMID 34843700, 2022). "In the present study we evaluate the expression, supramolecular organization and spatial distribution of AQP4 and AQP4ex, the new readthrough isoform of AQP4, in relationship with the degree of vasogenic brain edema and tumor progression." (PMID 35187599, 2022).
tumor (continued). "Identifying AQP4 protein in the composition of GBM-derived EVs can reflect apoptotic or aggressive molecular signatures of primary tumour indicative of aggressiveness or response to chemotherapy." (PMID 36071478, 2022). "Protein expression levels measured by immunoblot showed that global AQP4 was reduced mainly in the tumor core." (PMID 35187599, 2022). "In the present study, the expression of AQP4 was downregulated significantly in ccRCC tumor tissues and decreased with increasing clinical stage and pathological grade." (PMID 36254092, 2022). "Conversely, inhibition of PKC activity with chelerythrine reduced AQP4 phosphorylation, enhanced water permeability, and significantly enhanced tumor invasion." (PMID 35847914, 2022). "For instance, AQP4 has been shown to facilitate both changes in tumor cell morphology via polarizing the cell lamellipodia and increasing the number and size of lamellipodia in migrating tumor cells." (PMID 36010640, 2022). "The activation of PKC by two known PKC activators enhanced AQP4 phosphorylation, resulting in the reduced water permeability with significantly decreased tumor cell invasion." (PMID 35847914, 2022). "Tumor immunotherapy is a prominent topic in anti-tumor research, and the significance of AQP4 in immune modulation has yet to be discovered." (PMID 36523816, 2022). "Although the immunofluorescence revealed that the number of CD34+α-SMA+ arteries in the tumor area was more than in the contralateral area, the expression of AQP4 in the astrocytes around the vessels was weak in the tumor area." (PMID 35083148, 2021). "Tumor overexpression of the membrane water channel protein aquaporin-4 (AQP4), which regulates transcellular water movement and extracellular fluid resorption, has also been identified as a possible mechanism." (PMID 33828976, 2021). "Delong’s test result showed that ADCuh at tumor center versus Ki-67 and AQP4 versus Ki67 had significant differences (p < 0.05) among independent imaging parameters or molecular markers." (PMID 34712604, 2021). "Various potential risk factors contribute to the formation of PTBE, such as tumor-brain barrier disruption, tumor size, location, tumor margin shape, AQP4/TRPV4 channel co-expression, and vascular endothelial and lymphatic dysfunction." (PMID 34707993, 2021). "The staining intensity of vimentin and AQP4 was also significantly increased in the tumor mass compared to the contralateral hemisphere (p = 0.019 and p = 0.014, respectively)." (PMID 34441246, 2021). "High-power confocal microscopy revealed that, in the tumor, the surrounding of AQP4 by Evans Blue was decreased." (PMID 35083148, 2021). "Eleven of 43(11/43, 25.6%) patients performed AQP4 test in tumor tissue and seven of them were positive (7/11, 63.6%)." (PMID 34520629, 2021). "The KEGG data suggested that “synaptic vesicle cycle” and “phosphatidylinositol signaling system” were mainly involved in AQP4 effects on tumor pathogenesis." (PMID 34113257, 2021). "In the tumor group, the fluorescence intensity of GFAP in the tumor area was significantly higher, whereas the fluorescence intensity of AQP4 was significantly weaker." (PMID 35083148, 2021). "We further assessed the genetic alteration status of AQP4 in several tumor samples of the TCGA cohorts." (PMID 34113257, 2021). "We believe that the detection of AQP4 antibody in tumor tissue is the most direct method to confirm the origin of serum AQP4 antibody and the etiology of NMOSD." (PMID 34520629, 2021). "Upregulation of AQP4 can disturb the arrangement of orthogonal arrays of particles on the entire surface of tumor cells, resulting in changes in cytoskeletal and morphological structures." (PMID 32182968, 2020). "At the same time, expression of LINC00461 and AQP4 decreased in xenograft tumor tissues in sh-LINC00461 group, whereas miR-216a was higher." (PMID 33817241, 2020). "These outcomes showed a suppressive role of LINC00461 knockdown in tumor growth in vivo via miR-216a and AQP4." (PMID 33817241, 2020).
tumor (continued). "Anti-aquaporin 4 antibody, virologic and bacteriologic blood testing, screening of autoimmune disorders and occult neoplasm were all unremarkable." (PMID 31911876, 2019). "Since in parallel with vanishing from the capillaries, AQP4 accumulates at the border of the tumour, we conclude that this is rather an extraction of astrocyte end-feet from the vessels than loss of polarization, as previously suggested." (PMID 31426859, 2019). "Both the astrocyte-specific glial fibrillary acidic protein (GFAP) and the end-foot marker aquaporin-4 (AQP4) were localized between the partly or completely extravasated tumour cell and the capillary endothelium." (PMID 31426859, 2019). "Several studies have previously demonstrated a role for AQP4, a major water channel expressed in CNS astrocytes, in tumor edema and migration, the mechanisms of which are still incompletely understood." (PMID 30275445, 2018). "To gain mechanistic insight into how TEAD1 regulates tumor migration, we overexpressed AQP4 and CDH11 in sham and TEAD1KO spheroids and studied their migratory behavior." (PMID 30275445, 2018). "AQP4 is highly expressed at the leading edge of tumor cells, polarizing to and increasing the number and size of tumor lamellipodia to ensure water influx during cell movement." (PMID 30275445, 2018). "VEGF can induce angiogenesis, and AQP4 and VEGF likely act in concert during the process of tumor-associated edema formation." (PMID 28423683, 2017). "In MRI edematous areas, histologically characterized by an increased expression of Aquaporin 4, the identification of tumor cells depends on their frequency." (PMID 29207673, 2017). "Intracellular AQP4 redistribution was also significantly lower in tumor infiltration areas than in the tumor center, suggesting that the alteration of AQP4 expression pattern is specific for neoplastic regions." (PMID 27367682, 2016). "We found AQP4 and AQP1 were expressed that in infratentorial SEs throughout the entire tumor whereas in supratentorial SEs AQP4 and -1 were detected only in peripheral regions of the tumor but not in the center." (PMID 26115524, 2015). "In contrast, supratentorial subependymomas revealed aquaporin 4 and -1 expression only in border areas of the tumor." (PMID 26115524, 2015). "At first we focused in this study on different expression patterns of AQP4 and -1 in SEs and the possible correlation to the localization of the tumor." (PMID 26115524, 2015). "Perhaps as a reaction on this, AQP4 is upregulated and redistributed over the whole tumor cell surface." (PMID 22590566, 2012). "In the tumour progenitor population, aqp9 was markedly more highly expressed, whilst in tumour-derived differentiated cells, aqp4 was downregulated." (PMID 22262958, 2012). "In an orthotopic xenograft model for example tumor cells have been shown to change both basal lamina components and distribution and expression of AQP4." (PMID 22590566, 2012). "In tumour tissue, aqp4 expression was the most abundant (6.75 ± 2.86), but there was nearly as much aqp9 (5.37 ± 4.62) (mean ± SEM, n = 6, relative to aqp1 set to 1)." (PMID 22262958, 2012). "The immunofluorescence studies indicated that protein levels of aqp4 and 9 were low in tumour progenitors (tumourspheres) and highly expressed in the differentiated cells arising from them." (PMID 22262958, 2012). "Of note, AQP4 showed the strongest transcriptional deregulation between tumor and normal tissues (fold change: 0.11), the subtypes AC and SCC (6.0) and AC patient collectives with good and bad survival (4.4), respectively." (PMID 21548930, 2011). "Similarly, the use of AQP4 expression up-regulators would enhance edema fluid resorption in extracellular edema and could be combined with corticosteroid administration to more rapidly resolve edema associated with tumours and infection/inflammation." (PMID 21119879, 2010).
tumor (continued). "We hypothesize that an immune response against tumor-expressed AQP4 and GRP78 triggered the production of corresponding antibodies, with GRP78 antibodies contributing to BBB breakdown and the onset of paraneoplastic NMOSD." (PMID 41883892, 2026). "Therapies aimed at modulating AQP4 expression or localization may not only impede tumor spread but also recalibrate the immune landscape toward an anti-tumoral state." (PMID 41324079, 2025). "By reestablishing the polarized expression of AQP4 and preserving the dystrophin–dystroglycan complex, it may be possible to reinforce BBB function and attenuate tumor-associated edema and invasion." (PMID 41324079, 2025). "Moreover, non-coding RNAs such as lncRNA LINC00461 and miR-216a modulate AQP4 expression, further linking gene regulation to tumor behavior." (PMID 41324079, 2025). "These microenvironments exhibit altered water-efflux kinetics, suggesting that AQP4 may support cellular survival under cytotoxic stress by preserving ionic balance in hypo-perfused tumor zones, where drug diffusion is limited." (PMID 41324079, 2025). "In such zones, AQP4’s role in maintaining cell polarity and local fluid dynamics may buffer against treatment-induced apoptosis, enabling tumor cell regrowth." (PMID 41324079, 2025). "In a paraneoplastic context, such an expansion could theoretically represent the specific lymphocyte clones that are reacting to the tumor antigen (e.g., AQP4), thereby providing a molecular fingerprint of the paraneoplastic response." (PMID 40963604, 2025). "However, it has been proposed that AQP4 regulates tumour cell migration and invasion through cytoskeleton reorganization and cell adhesion modulation." (PMID 38336645, 2024). "Here, we attempted to identify potential regulators that could interfere with some degree of regulation of the disposition and function of AQP1 and AQP4 in tumor cells." (PMID 38476871, 2024). "Concomitant with the overexpression of AQP4, genes related to the immune system were also over-expressed, such as CD74, HES1, CALD1, and HEBP2, indicating AQP4 may relate to immune factors of tumor progression." (PMID 36599974, 2023). "Furthermore, AQP4 is highly expressed in tumours, promoting peritumoural oedema and opening of the blood–brain barrier." (PMID 38067243, 2023). "Aquaporin-4 (AQP4) is a critical molecule in the central nervous system that participated in preserving water and ion homeostasis and has been indicated to play a key role in tumor cell invasion." (PMID 36740668, 2023). "This reflected the regulation of gene expression in necrosis (autophagy genes), peritumoral tissue (vascular endothelial growth factor gene), and edema (angiogenesis genes); in particular, aquaporin-4 water channels contribute to extended tumor cell migration in tumor edema." (PMID 36991494, 2023). "Some researchers believe that gland expansion may be due to the overexpression of aquaporin 4 (AQP4) in tumor cells, resulting in an excessive water inflow." (PMID 38162862, 2023). "Likewise, the inhibition of PKC activity reduced AQP4 phosphorylation with enhanced water permeability and tumor cell invasion." (PMID 35847914, 2022). "Moderate changes in AQP4 pools abundance were observed with tumor progression." (PMID 35187599, 2022). "Indeed, in mice models, melanoma cells implanted into the striatum of wild-type and AQP4-null mice produced edema surrounding the tumor mass and comparable sized-tumors in both groups after a week." (PMID 35847914, 2022). "Here, we tested the hypothesis that phenotypic features reported for GBM cells expressing AQP4 tetramers or AQP4-OAPs could be exported, via EVs, to recipient tumour cells and influence their features." (PMID 36071478, 2022). "Although the mislocalization of AQP4 was proposed to be a mechanism of alleviating benign disease, such as autoimmune mediated CNS pathophysiology, it may also be useful for designing anticancer therapeutic targets." (PMID 35847914, 2022).
tumor (continued). "One study reported that peritumoral brain edema may depend on the aquaporin-4 (AQP4) expression level, which is now considered a biomarker reflecting tumor malignancy." (PMID 36530973, 2022). "AQP4 gene expression was found to be substantially linked with microsatellite instability (MSI) but not with tumor mutational burden (TBI), immunological score, stromal score, or tumor purity." (PMID 36523816, 2022). "At least two factors could be involved in AQP4 alteration in GBM: the tumor microenvironment and the extracellular matrix." (PMID 35187599, 2022). "Moreover, they emphasized the link between AQP4 and physiological lung function, which appears to decrease with advancing tumor dedifferentiation." (PMID 36233821, 2022). "Moreover, it has been suggested that a polarized rearrangement of AQP4 expression in peri-tumoral area specimens after combined chemotherapy and radiotherapy can lead into the normalization of tumor blood vessels." (PMID 35847914, 2022). "Pathological staining of tumor sections revealed a high AQP4 expression." (PMID 36530632, 2022). "We hypothesize that the higher tumor ADC may reflect water increase in the tumor interstitium as a consequence of AQP4-mediated fluid influx." (PMID 34722268, 2021). "This led us to question why Evans Blue decreased around the tumor area and whether it was related to AQP4 on the foot process of astrocytes." (PMID 35083148, 2021). "If the serum AQP4 is positive, it is best to do further AQP4 immunostaining of tumor tissue." (PMID 34520629, 2021). "Some studies found that inhibition of AQP4 expression resulted in slowed tumor growth." (PMID 34113257, 2021). "In this scenario, it was feasible that SNX27 downregulation in Kidins220f/f mice could lead to lysosomal processing of AQP4 in astrocytes, as it occurs with Kidins220 after SNX27 loss in tumour cells." (PMID 34002021, 2021). "The correlation analysis between DWI-derived imaging parameters and histological indices revealed that expression of AQP1, AQP4 and Ki67 were correlated with ADCst, f, ADCslow and ADCuh at the center of the tumor while had little correlation with those of peritumoral imaging parameters." (PMID 34712604, 2021). "However, increased levels of AQP4 and AQP4/TRPV4 co-expression were detected in most tumors with larger edema whereas upregulation of AQP4 was found in peri-tumor tissue." (PMID 33538957, 2021). "Therefore, we cannot definitely state that the ALPS index is a measure of glymphatic function, and the changes of tumor ADC were due to the expression of AQP4 and fluid volume increase in the tumor interstitium." (PMID 34722268, 2021). "However, as a metastatic lesion is growing, AQP4-positive astrocyte end-feet are disappearing from the vessel to cover the surface of the tumour, from which reactive astrocytes are completely expelled." (PMID 31426859, 2019). "In glioma cells, miR-320a overexpression down-regulates AQP4 and diminishes cell invasion and migration, suggesting it could be used as a therapeutic target to suppress the aggressive capacity of this tumor." (PMID 29977890, 2018). "In addition to normal astrocytes, AQP4 is also expressed in human astrocytomas where the level of expression correlates with tumor aggressiveness." (PMID 29977890, 2018). "It has been reported that AQP4 could dissociate from OAPs and redistribute across the entire surface of tumor cells." (PMID 28423683, 2017). "The redistribution of AQP4 and OAPs could be observed in the infiltration zone around the tumor proper in which the neurovascular unit appeared normal and histologically unaltered regarding the morphology." (PMID 28423683, 2017). "Despite this controversy, comparisons between the tumor center and perifocal infiltration zone regarding AQP4 expression levels might be the key to clarifying the role of the AQP4 expression profile in predicting tumor progression." (PMID 28423683, 2017).